LTBR (lymphotoxin beta receptor)
Diseases named in the same sentence as LTBR in open-access papers (continued):
Sharing a sentence is not in itself a finding about the gene and the disease.
multiple sclerosis (2 papers, 2018 to 2023). A progressive autoimmune disorder affecting the central nervous system resulting in demyelination. "This multiple sclerosis risk locus contains two plausible causal genes (TNFRSF1A and LTBR) and two independent signals for multiple sclerosis risk (rs1800693 and rs2364485)." (PMID 37563310, 2023). "The multiple sclerosis risk allele is associated with lower expression of LTBR and higher circulating protein levels of LTA, a component of its ligand." (PMID 37563310, 2023). "Taken together, these data are consistent with a pathogenic model whereby the multiple sclerosis risk allele results in lower abundance of LTBR (the receptor) and consequently higher circulating levels of the ligand LTA." (PMID 37563310, 2023). "In multiple sclerosis animal models, LTβR signaling plays a detrimental effect on both demyelination and remyelination via T cells and/or local astrocytes/microglia." (PMID 29463313, 2018).
pancreatic endocrine tumors (2 papers, 2018 to 2021). "Important to note is that anti-angiogenic immunotherapy in the form of anti-VEGF plus anti-PDL1 induced the noncanonical LTβR pathway in ECs of breast and pancreatic endocrine tumors, which enabled HEV formation, enhanced lymphocyte infiltration, and prolonged survival of tumor-bearing mice." (PMID 34484246, 2021).
psoriasis (2 papers, 2022 to 2026). An autoimmune condition characterized by red, well-delineated plaques with silvery scales that are usually on the extensor surfaces and scalp. "The expression of HVEM and LTBR (another LIGHT receptor) has been found to be increased in the skin of psoriasis patients." (PMID 41684072, 2026). "In this study, we verified the psoriasis susceptibility genes IFIH1 (2q24.3), ERAP2 (5q15), IL18R1 (2q12.1), LTBR (12p13.31), IL1RL1 (2q12.1), CARD14 (17q25.3), and SLC9A4 (2q12.1)." (PMID 36425068, 2022).
renal fibrosis (2 papers, 2020 to 2022). A final common manifestation of a wide variety of chronic kidney diseases characterized by glomerulosclerosis and tubulointerstitial fibrosis. "In the present study, we found that the expression of TNFSF14 and its receptors HVEM and LTβR were rapidly up-regulated in UUO-induced mouse renal fibrosis model and in patients with fibrosis nephropathy." (PMID 33231567, 2020). "In conclusion, our study supports the pivotal effect of the LIGHT-HVEM/LTβR signaling in mediating I/R-AKI and I/R-induced renal fibrosis." (PMID 36163116, 2022).
skin cancer (2 papers, 2021 to 2025). "LTβR is expressed in various cancer cells, particularly in lung and skin cancers." (PMID 40883295, 2025).
Splenomegaly (2 papers, 2021). Abnormal increased size of the spleen. "LTβR-/- mice are known to develop splenomegaly due to increased numbers of splenocytes and neutrophils." (PMID 34335629, 2021). "This is in accordance with the finding that LTβR−/− animals present with splenomegaly, probably due to microbiota-mediated inflammation." (PMID 33753412, 2021). "LTβR-/- mice develop an autoimmune phenotype such as splenomegaly, production of autoantibodies and lymphocytic infiltrations to non-lymphoid organs." (PMID 34335629, 2021). "Paradoxically, LTβR-/- mice exhibit an autoimmune phenotype which includes splenomegaly, autoantibody production and systemic inflammation with increased neutrophil numbers in spleen and multiple lymphocytic lymphoid infiltrates in non-lymphoid organs." (PMID 34335629, 2021). "This is also supported by our findings that LTβR−/− mice do not show the typical splenomegaly associated with (T. gondii) infection." (PMID 33753412, 2021). "Our results demonstrate that inactivation of LTβR signaling during adulthood in iLTβRΔ/Δ mice did not result in splenomegaly, infiltration of immune cells to non-lymphoid organs, impairment of thymus microarchitecture, or reduction of thymic Aire expression." (PMID 34335629, 2021).
acute kidney injury (1 paper, 2024). Sudden and sustained deterioration of the kidney function characterized by decreased glomerular filtration rate, increased serum creatinine or oliguria. "However, the functions and underlying mechanisms of LTβR in acute kidney injury (AKI) remain largely unknown." (PMID 39707217, 2024).
allergic asthma (1 paper, 2014). A asthma with a basis in a pathological type I hypersensitivity reaction. "LIGHT induces asthmatic cytokine IL-13 and fibrogenic cytokine transforming growth factor-β release from allergic asthma-related eosinophils expressing HVEM and alveolar macrophages expressing LTβR, respectively, thereby playing crucial roles in asthmatic airway remodeling." (PMID 24782592, 2014).
alveolitis (1 paper, 2008). "Further pulmonary microvascular damage with alveolitis, plasma and erythrocyte leak in the alveolar space seen in control mice was also reduced in LTβR-deficient mice." (PMID 18612394, 2008).
anaemia (1 paper, 2008). "Further, absence of LTα or LTβR did not interfere with the progression of blood stage infection, and LTα or LTβR deficient mice succumb within 3 weeks of severe parasitaemia and anaemia." (PMID 18612394, 2008). "The ECM resistant, LTβR deficient mice further developed dramatic anemia, similar to LTα deficient mice (1.34±0.30×106 RBC/μL), and probably succumb of general hypoxia after 3 weeks." (PMID 18612394, 2008). "LTβR deficient mice, similar to wild-type mice, showed thrombocytopenia and decreased lymphocyte counts at day 7 when mice show signs of incipient CM, together with a slight anemia and slight increase in parasitaemia, that further increased thereafter." (PMID 18612394, 2008). "In contrast, LTβR deficient mice reconstituted with wild-type bone marrow displayed protection to ECM comparable to LTβR deficient mice reconstituted with LTβR deficient bone marrow, and further developed severe fatal anaemia, but no cerebral syndrome." (PMID 18612394, 2008). "LTβR deficient mice did not develop the neurological signs seen in PbA induced ECM but died at three weeks with high parasitaemia and severe anemia like LTαβ deficient mice." (PMID 18612394, 2008). "In conclusion, the resistance to ECM development of LTα and LTβR deficient mice was not attributable to decreased parasitaemia or thrombocytopenia, and the ECM resistant mice developed very high parasitaemia and died of severe anemia within 3 weeks." (PMID 18612394, 2008). "We then asked whether parasitaemia and anemia are influenced in the absence of LTβR signaling." (PMID 18612394, 2008).
arteritis (1 paper, 2018). An inflammatory process affecting an artery. "There was only a moderate correlation between active tubulitis/interstitial inflammation (atii) and the expression level of Ltβ mRNA (p<0.05) and active arteritis (av) and the expression of the LTβR mRNA (p<0.05) when patients from all groups were analyzed together." (PMID 29300739, 2018).
chronic hepatitis (1 paper, 2012). An active inflammatory process affecting the liver for more than six months. "Additionally, pharmaceutical long-term blockage of the LTβR, using LTβR-Ig, led to significantly decreased chronic hepatitis rates in tg1223 mice." (PMID 23233866, 2012).
chronic viral hepatitis (1 paper, 2016). "CXCL10 is expressed by hepatocytes during chronic viral hepatitis, induced by LTβR activation via NF-κB and is considered as one of the main chemoattractants for tumour-infiltrating immune cells." (PMID 26206664, 2016).
colorectal tumor (1 paper, 2012). "The ability of radiation to modulate the expression of multiple death receptors (Fas/CD95, TRAILR1/DR4, TRAILR2/DR5, TNF-R1 and LTβR) was examined in colorectal tumor cells." (PMID 22389673, 2012). "Overall, these data reveal that sub-lethal doses of IR induce increased expression of some death receptors (Fas, DR4 and DR5) but not all TNF related death receptors (LTβR and TNF-R1) in colorectal tumor cells." (PMID 22389673, 2012).
delirium (1 paper, 2023). A disorder characterized by confusion; inattentiveness; disorientation; illusions; hallucinations; agitation; and in some instances autonomic nervous system overactivity. "None of the delirium-associated proteins in preoperative plasma were the same in both age groups, whereas in postoperative samples the age groups had 3 such proteins (IL-8, lymphotoxin beta receptor [LTBR], tumor necrosis factor receptor 2 [TNFR2]) in common." (PMID 37156856, 2023). "A few proteins (IL-8, LTBR, TNF-R2 postoperatively; IL-8, IL-6, LIF, ASGR1 by pre- to postoperative change) and 12 networks were common to delirium in both age groups." (PMID 37156856, 2023).
fibrosis (1 paper, 2023). the formation of excess fibrous connective tissue in an organ or tissue in a reparative or reactive process. "Notably, expression of LIGHT, HVEM, and LTβR were significantly correlated with fibrosis severity in the lacrimal sac walls." (PMID 37465675, 2023). "Given that HVEM deletion reduced dermal fibrosis to a greater extent than deletion of LTβR, this may suggest that HVEM profibrotic signaling in dermal fibroblasts is more potent that LTβR signaling." (PMID 37465675, 2023).
glioma (1 paper, 2022). A benign or malignant brain and spinal cord tumor that arises from glial cells (astrocytes, oligodendrocytes, ependymal cells). "In situ protein validation from glioma samples of the Human Protein Atlas confirmed the expression of LTBR protein in different samples in cells that had the morphological features of ramified microglia cells and foamy macrophages." (PMID 36230839, 2022).
glomerulonephritis (1 paper, 2018). A renal disorder characterized by damage in the glomeruli. "Also earlier studies from our group in patients with various forms of glomerulonephritis, demonstrated that LTβR expression was unaltered in inflamed kidneys." (PMID 29300739, 2018).
head and neck cancer (1 paper, 2023). A primary or metastatic malignant neoplasm affecting the head and neck. "Furthermore, another study revealed that activated LTBR can promote tumor cell migration and metastasis by activating the NF-κB signaling cascade in head and neck cancer." (PMID 37366426, 2023). "A previous study found that LTBR was increased in head and neck cancer, which could induce tumor cell migration." (PMID 37366426, 2023). "In line with the present study, a previous study demonstrated that LTBR could induce the activation of the NF-κB pathway in head and neck cancer." (PMID 37366426, 2023).
helminth infection (1 paper, 2017). "Here we demonstrate a crucial role for lymphotoxin-beta receptor (LTβR) signaling to fibroblastic reticular cells (FRCs) by lymphotoxin-expressing B cells in driving mesenteric lymph node lymphangiogenesis following helminth infection." (PMID 28848229, 2017).
hepatoblastoma (1 paper, 2016). Hepatoblastoma (HB) is a malignant hepatic tumor and is the most common pediatric liver cancer. "Moribund livers following 8 weeks of anti-LTβR or Ig treatment displayed a preponderance of lipogenic foci with mean histological scores of 3.7 for anti-LTβR and 3.5 for Ig and similar incidence of hepatoblastoma/HCC-like tumours following agonism." (PMID 26206664, 2016).
Hyperglycemia (1 paper, 2025). An increased concentration of glucose in the blood. "They found attenuation of the upregulation of LIGHT receptors (LTβR and HVEM) that occurred in engrafted human islets exposed to hyperglycemia by IL-22." (PMID 40422866, 2025).
immune deficiency (1 paper, 2021). "The results obtained in this study corroborate a profoundly deficient immune response of LTβR−/− mice to T. gondii infection and reveal an impaired IFN response, a severe functional T cell defect, as well as a humoral immune deficiency in the absence of LTβR." (PMID 33753412, 2021).
intestinal infection (1 paper, 2016). "Surprisingly however, recombinant IL-22 administration can restore TLT formation in the colon of LTβR-deficient mice, suggesting that IL-22 can directly and independently impact TLT organization during intestinal infection." (PMID 27579025, 2016). "A governing signal that drives both IL-22 and CXCL13 expression is integrated by LTβR, with LTβR initiating an ILC-DC cross talk via IL-23 to induce IL-22 following intestinal infection with Citrobacter rodentium." (PMID 27579025, 2016).
ischemia (1 paper, 2008). A hypoperfusion of the BLOOD through an organ or tissue caused by a PATHOLOGIC CONSTRICTION or obstruction of its BLOOD VESSELS, or an absence of BLOOD CIRCULATION. "Resistance of LTαβ or LTβR deficient mice correlated with unaltered cerebral microcirculation and absence of ischemia, as documented by magnetic resonance imaging and angiography, associated with lack of microvascular obstruction, while wild-type mice developed distinct microvascular pathology." (PMID 18612394, 2008).
kidney injury (1 paper, 2022). Trauma to the kidney. "Our results showed that blocking LIGHT-HVEM/LTβR pathway alleviates I/R-induced kidney injury, which further supports the potential clinical efficacy of LIGHT inhibitors for I/R-AKI in humans." (PMID 36163116, 2022).
large cell carcinoma (1 paper, 2019). A malignant epithelial neoplasm composed of large, atypical cells. "In addition, squamous cell carcinomas had lower expression levels of membranous RANK and higher levels of nuclear LTβR compared to adenocarcinomas and large cell carcinomas (p = 0.018 and p = 0.020, respectively)." (PMID 31137630, 2019).
lymphopenia (1 paper, 2023). Reduction in the number of lymphocytes. "By turning off IL7 transcripts and promoting myeloid cell egress, LTβR, in combination with TNFR and IL-1R signaling in MSCs, acts as a molecular switch between homeostatic hematopoiesis and a temporary state of lymphopenia that is required for emergency myelopoiesis to proceed." (PMID 36717247, 2023).
myxoma (1 paper, 2022). A benign soft tissue neoplasm characterized by the presence of spindle and stellate cells, lobulated growth pattern, and myxoid stroma formation. "Finally, we checked the expression levels of lymphotoxin-β receptor (LTβR) and herpes virus entry mediator (HVEM) since the transgene (LIGHT) used to arm the myxoma construct can regulate the activity of T lymphocytes via binding to these two receptors." (PMID 35454928, 2022).
Neonatal respiratory distress (1 paper, 2025). Respiratory difficulty as newborn. "Notably, Etanercept and Asciminib hydrochloride, which function as LTBR gene activators and maintain normal LTBR gene expression, emerge as promising therapeutic candidates for neonatal respiratory distress through their LTBR activation mechanism." (PMID 40388790, 2025).
non-Hodgkin lymphoma (1 paper, 2014). Distinct from Hodgkin lymphoma both morphologically and biologically, non-Hodgkin lymphoma (NHL) is characterized by the absence of Reed-Sternberg cells, can occur at any age, and usually presents as a localized or generalized lymphadenopathy associated with fever and weight loss. "Moreover, both ligand (LT-β) and receptor (LTβR) have been shown expressed in non-Hodgkin's lymphoma cells including MCL, which potentially leads to constitutive activation of NF-kB signaling, suggesting a pathogenic role of the LT-β/LTβR axis in lymphomagenesis." (PMID 25211095, 2014).
odontogenic keratocysts (1 paper, 2019). "LTBR plays a role in lymphoid development signaling and the immune response, and the hypermethylation of LTBR is observed in odontogenic keratocysts, though its expression is not affected." (PMID 31796052, 2019).
pituitary adenomas (1 paper, 2025). "Additional genes—PHYHD1, LTBR, MYBPHL, C22orf42, PRR5, ANKDD1A, RAB13, CAMKV, KIFC3, WNT4, and STAT6—were implicated in the invasive behavior of non-functioning pituitary adenomas (NFPAs)." (PMID 39859246, 2025).
primary immunodeficiency diseases (1 paper, 2012). "TRAF3 regulates both innate and adaptive immunity by modulating signaling mediated by various receptors such as Toll-like receptors, TNF receptors, and lymphotoxin-β receptor (LTBR), and deficiency of TRAF3 has also been implicated in primary immunodeficiency diseases." (PMID 22709905, 2012).
prion disease (1 paper, 2015). A transmissible disease that is caused by a protein that is able to induce abnormal folding of normal cellular proteins, leading to characteristic spongiform brain changes, which are associated with neuronal loss without an inflammatory response. "However, whereas all control mice orally exposed to prions at 21 days old succumbed to clinical prion disease, those with LI FDC-containing GALT only at the time of exposure displayed dramatically reduced disease susceptibility (21-day-old LTβR-Ig-treated mice)." (PMID 26157121, 2015).
renal dysfunction (1 paper, 2022). "Consistently, blocking LIGHT signaling with its soluble receptor fusion proteins (HVEM-IgG-Fc or LTβR-IgG-Fc) improved I/R renal dysfunction." (PMID 36163116, 2022).
salivary gland disease (1 paper, 2009). "The aim of the present study was to analyze the effects of LT/LIGHT axis blockade by the pharmacological inhibitor LTβR-Ig on SS-like salivary gland disease in female NOD mice, introducing the inhibitor prior to the development of the SS-like disease." (PMID 19222863, 2009).
sarcoidosis (1 paper, 2025). Sarcoidosis is a multisystemic disorder of unknown cause characterized by the formation of immune granulomas in involved organs. "Additionally, three out of the four proteins preliminarily identified for sarcoidosis—VEGFB (coloc.abf-PPH4 = 0.907), LTBR (coloc.abf-PPH4 = 0.947), and ANGPTL4 (coloc.abf-PPH4 = 0.957)—received robust support by genetic colocalization analysis (PPH4 > 0.8) under standard priors and window (± 1 Mb)." (PMID 39824903, 2025).
scrapie (1 paper, 2012). A fatal disease of the nervous system in sheep and goats, characterized by pruritus, debility, and locomotor incoordination. "To confirm this result quantitatively, we analyzed prion infectivity in mLNs from Ig-treated versus LTβR-Ig-treated WT and TNFR1−/− mice using the scrapie cell assay (SCA;)." (PMID 22912582, 2012).
squamous cell carcinoma (1 paper, 2019). A carcinoma arising from squamous epithelial cells. "On the contrary, OS was not affected by LTβR expression in patients with squamous cell carcinomas (n = 1926, p = 0.42)." (PMID 31137630, 2019).
Thrombocytopenia (1 paper, 2008). A reduction in the number of circulating thrombocytes. "The hematological investigations at 7 days after infection revealed distinct reductions of platelet counts in C57BL/6 mice as compared to non-infected mice, as reported, and we show a similar thrombocytopenia in the ECM resistant LTβR deficient mice." (PMID 18612394, 2008).
viral pneumonia (1 paper, 2026). Inflammation of the lung parenchyma that is caused by a viral infection. "Along with evidence of roles for TNFSF14 and LTβR in safeguarding AMs, there is enthusiasm for further considering TNFSF14 or LTβR blockade in viral pneumonias." (PMID 41542776, 2026). "Blocking TNFSF14 or the LTβR during severe viral pneumonia is intriguing as a potential therapeutic approach." (PMID 41542776, 2026).
ZIKV infection (1 paper, 2025). "This protein preferentially inhibits nuclear factor kappa B (NF-κB) signaling and the production of inflammatory cytokines by interfering with the dimerization of lymphotoxin-β receptor (LTβR), thereby enhancing ZIKV infection in cells in vitro and exacerbating its pathogenesis in mice in vivo." (PMID 39858476, 2025).